IGHG1 (immunoglobulin heavy constant gamma 1 (G1m marker))
Diseases named in the same sentence as IGHG1 in open-access papers (continued):
Sharing a sentence is not in itself a finding about the gene and the disease.
tumor (continued). "Our findings enlarge the understanding of IGHG1 in tumor regulation." (PMID 34315496, 2021). "As a result, IGHG1 overexpression vector transfection drastically increased tumor cell migration and proliferation compared with control group, while combinatory transfection with β-Catenin siRNA abolished tumor cell migrative and proliferative superiority." (PMID 34315496, 2021). "Moreover, transwell assay also indicated that tumor cells with IGHG1 overexpression demonstrated that significantly increased cellular migrative and invasive capabilities compared with control groups." (PMID 34315496, 2021). "In our study Ighg1 downregulation was associated with increased tumor burden and thus Ighg1 is not promoting tumorigenesis in the SPC-IGFIR-Akt2−/− mice." (PMID 26654940, 2016). "Interestingly, the most important functional subtype of Ig expressed by pancreatic cancer cells, Igγ-1 chain C region (IGHG1), may be involved in tumor cell proliferation and immune escape mechanism." (PMID 40535807, 2025). "The expression of IGHG1 was positively relevant to tumor grade and could predict adverse prognosis." (PMID 34760705, 2021). "In the CR mechanism, the identified biological processes with IGHG1 and VTN proteins were tumor cell growth and the microenvironment of the tumor cells." (PMID 40079446, 2025). "Our data indicated that the “cold” tumor types like MB and EPN also contained the major classical immune cells, such as T cells (PTPRC, CD3D), B cells (CD79A, IGHG1, MZB1), and NK cells (KLRB1)." (PMID 38094301, 2023). "ASCs in tumour tissues with NACT expressed the highest levels of XBP1 and IGHG1 among the three tissue source types and the proportion of XBP1‐positive cells was the largest in tumour tissues with NACT among the three tissue source types." (PMID 36650114, 2023). "Immune infiltration analysis indicated that the expression level of IGHG1 was positively correlated with the stromal score, ESTIMATE score, and immune score and negatively correlated with tumor purity." (PMID 34760705, 2021). "To take another approach to estimate the relation of IGH mRNAs with processes in the tumor we performed correlation analyses of IGHA2 and IGHG1 mRNAs with all other mRNAs, expressed as log2 of the FPKM, obtained with the Tuxedo RNA-Seq analysis pipeline." (PMID 32656317, 2020). "Immunoglobulin heavy constant gamma 1 (IGHG1) and transmembrane 4 L six family member 19 (TM4SF19) were related to tumor immune invasion mechanisms and then made the tumor cells immunity." (PMID 23577100, 2013). "In analyzing B cells in the tumor microenvironment, B cells were separated into two clusters: one termed as follicular B cell, with high expressions of MS4A1, CD79B, CD52, and another termed as plasma cell, with high expressions of IGHG1, IGHG4 and MZB1." (PMID 38443340, 2024). "We found IGHG1 and IGHG3 were significantly enriched in Myeloid Predominant compared to Immune Neutral and Immune Desert (two-sided Student’s t test, p = 0.03 and 0.008), suggesting that potential antibody-producing cells infiltrated these tumours." (PMID 37679810, 2023). "Here, the silence of IGHG1 reduced the heme content in HT29 cells and exerted anti-tumor role." (PMID 34553073, 2021). "IGHG1 is not exclusively to the immune cells, and it has been detected in human cancer tissue samples from breast, lung, and oral epithelial tumors, and also in human tumor cell lines." (PMID 23977302, 2013). "The neutral effect of both IGHG1/MS4A1 ratio and IgG1 clonality in KRASmut tumors suggests that IgG1-producing plasma B-cells do not play a prominent role as key drivers of anti-tumor response via ADCC in this subtype of LUAD." (PMID 31665076, 2019).
cancer (38 papers, 2011 to 2025). A tumor composed of atypical neoplastic, often pleomorphic cells that invade other tissues. "CR clots exhibited high levels of proteins associated with active cancer and immune responses, such as IGHG1 and VTN." (PMID 40079446, 2025). "The expression of IGHG1, which encodes the constant region of immunoglobulin heavy chain, is positively correlated with cancer-IgG." (PMID 34760705, 2021). "Cancer‐associated genes (VIM, IGHG1‐4, IGKC, IGHA1) were upregulated, and CPCAT data revealed correlations of IREB2 with IGHG1 and VIM, and CD27 with IGHG1." (PMID 41377765, 2025). "Among cancer and precancerous lesions glycoproteins, we further highlight seven glycoproteins found in high-grade dysplasia as well as cancer (IGHG1, CPA2, MYH2, AZU1, PRTN3, CA1, SMPDL3B), holding potential for non-invasive detection of aggressive traits." (PMID 38612533, 2024). "Immunoglobulin heavy constant chain gamma 1 (IGHG1) is highly expressed in a variety of cancers and is considered an emerging prognostic marker." (PMID 36883223, 2023). "Consistent with findings in adult cancers, IGHG1 constituted the largest proportion of B-cell repertoire relative to total number of isotypes." (PMID 37679810, 2023). "By constructing siRNA that targets the IGHG1 (immunoglobulin heavy constant gamma 1) gene, we performed cancer-IgG knockdown within PC9 and H292 cells; siRNA2 presented to be more efficient." (PMID 34150640, 2021). "As a result, IGHG1 overexpression significantly increased cellular survivability under pressures of three chemo-agents, while IGHG1 silencing obviously inhibited cancer cell viabilities." (PMID 34315496, 2021). "Representatively, B cell and humoral immune response marker gene IGHG1 demonstrates a gene expression pattern of gradual up-regulation from normal cells to cancer cells, and then slightly droops." (PMID 33224891, 2020). "The expression of IgG1 heavy chain gamma 1 (IGHG1) and cancer-IgG were detected by bioinformatics and immunohistochemistry in NSCLC; The gene set enrichment analysis (GSEA) method was used to explore the signaling pathways involved in IGHG1 regulation." (PMID 31196367, 2019). "Firstly, increased activation of MEK and ERK was found with increased phosphorylation in cultured PCa cell line, and inhibition of IGHG1 reduced this activation, indicating that IGHG1 functioned via MEK/ERK/c-Myc axis to regulate PCa cancer growth." (PMID 31355278, 2019). "IGHG1 and Igκ were both successfully amplified following isolation of the cancer cells from frozen CRC samples." (PMID 23133595, 2012). "A study on glial cancer has shown that IGHG1 can play an interfering role in the immune system’s fight against cancer cells, thus inducing immune escape of cancer cells, making the expression of IGHG1 negatively correlated with the survival rate of patients and their prognosis." (PMID 40566633, 2025). "In most cancer patients, there is a switch to IGHG1-expressing plasma cells." (PMID 38036590, 2023). "Our results suggested that the expressions of IGHG1 and cancer-IgG could induce immune escape, contributing to poor survival." (PMID 34760705, 2021). "IGHG1 has been shown to promote the metastasis of gastric and ovarian cancer." (PMID 34553073, 2021). "In the generally ER-positive Luminal A and B subtypes the association was not significant with the exception for IGHG1 in Luminal A cancers restricted to patients with age at diagnosis below 65 years (HR: 0.50, 95% CI: 0.26, 0.96)." (PMID 32656317, 2020). "The relationship between IGHG1 and many cancers has been identified during recent years." (PMID 31355278, 2019). "Inhibition of IGHG1 suppresses cancer cell growth in vitro and in vivo." (PMID 31355278, 2019). "siRNA targeted silencing of IGHG1 has been shown to inhibit cell viability and promote apoptosis, which might therefore act as a potential target in cancer gene therapy." (PMID 30700767, 2019).
cancer (continued). "IgG mRNA (IGHG1) was detectable in the cytoplasm of cancer cells with in situ hybridization." (PMID 23133595, 2012). "Furthermore, IGHG1 mRNA levels, which were not as strongly associated with prognosis in basal-like cancers, display a higher correlation with immune cell metagenes than IGHA2 mRNA." (PMID 32656317, 2020). "Most of these proteins are recognized as potential prognostic biomarkers in liver (TFRC and GPLD1), renal (IGHG1, PRCP, SAA1/2, and IL1RAP) and digestive (PRSS3) cancers in the Human Protein Atlas database." (PMID 41155404, 2025). "Comparing the mRNA expression levels of top 8 DEGs in tissue samples, IGHG1 and S100A6 were found at higher expression levels in cancer tissues (P < 0.001)." (PMID 38898490, 2024). "CCL15 was also increased as the pseudo-time progressed and was dominant in the end stages of the pseudo-time axis; Conversely, other key molecules such as IGHG1, IGHG3, IGHG4, IGKC, IGLC2 decreased gradually among all the carcinoma sectors in HCC1 and HCC4." (PMID 35673582, 2022). "Additionally, immunoprecipitation-mass spectrometry (IP-MS) revealed that TAM-derived CXCL1 interacts with immunoglobulin heavy constant gamma 1 (IGHG1) in CRC cells, and enhances cancer cell proliferation and migration." (PMID 39606777, 2024). "The biological functions of IGHG1 and IGHG3 expression in cancer cells remains unclear despite some reports showing that IgG secreted by cancer cells had some unidentified capacity to promote the growth and survival of cancer cells." (PMID 23977302, 2013). "Additionally, volcano plots of the differentially expressed genes in these cancers indicated that in the RAC1 low-expression group, the expression levels of B cell surface markers (such as CD19, CD79A, and MS4A1) and immunoglobulin-related genes (such as IGHG1 and CR2) were higher." (PMID 39898257, 2025).
infection (10 papers, 2021 to 2025). The state of being infected such as from the introduction of a foreign agent such as serum, vaccine, antigenic substance or organism. "Furthermore, the frequencies of BCR clonotypes with IGHG1 constant sequence (IgG1) increased after infection relative to IgG2 in all patients." (PMID 34395931, 2021). "Among them, the expression level of IGHG1 in the pre-vaccination group was lower and more stable compared with the other four groups, suggesting that IGHG1 may play an important role in the immune response generated by the organism after infection with SARS-CoV-2." (PMID 40566633, 2025). "The overlap between patient samples collected during late acute phase and A549 infection included genes involved in response to immune stimulus such as CCL16 and IGHG1." (PMID 39065267, 2024). "We reported a high expression of IGHG family (IGHG1, IGHG2, and IGHG3) and IGLV family (IGLV3-21 and IGLV6-57) at 0 weeks, which are clinically correlate with active infection." (PMID 37434783, 2023). "An increased expression of IGHG1, IGHG2, IGHG3, IGLV3-21, and IGLV6-57 was noted during active infection at 0 weeks compared with that at 8 weeks." (PMID 37434783, 2023). "Germline transcription of Ighg1, Ighg3, Ighg2b, and Ighg2a/c was greatly enhanced in CD5- B-1b cells from A/J compared to C57BL/6J mice on day 5 of secondary infection, suggesting heightened isotype class switching occurred in mice in the resistant background." (PMID 34871323, 2021). "In plasma cells, PCV2 infection reduced the expression of Igha, upregulated the expression of Ighm, and did not significantly affect the expression of Ighd, Ighg1, Ighg2b, and Ighg3." (PMID 41011514, 2025). "In addition, since IGHG1 is up-regulated 7 days after infection with SARS-CoV-2, it is shown that IGHG1 produced after infection with SARS-CoV-2 plays an important role in long-term immune memory and helps the body to respond quickly when faced with the same pathogen in the future." (PMID 40566633, 2025). "Thus, we hypothesize that IGHG1 and LGALS1, detected early in E. granulosus infection, induce EMT initiation in the host liver cells; this results in vimentin expression in the middle infection stage, followed by persistent increases in expression in the late infection stage." (PMID 39625960, 2024).
IGHG1 also shares sentences with these, for which no sentence is quoted: asthma (3 papers); Huntington disease (2); lung carcinoma (2); ovarian carcinoma (2); Amoebiasis (1); autoimmune disease (1); bladder cancer (1); blood cancer (1); Crohn disease (1); diabetes (1); dilated cardiomyopathy (1); glioblastoma (1); hairy cell leukemia (1); Heat Stroke (1); joint disease (1); lung diseases (1); lupus nephritis (1); malignant mesothelioma (1); Mendelian diseases (1); nephritis (1); Parkinson disease 7 (1); periodontitis (1); Primary immunodeficiency (1); prion disease (1); seminoma (1); staphylococcus aureus infection (1).